NAMA (non-protein coding RNA, associated with MAP kinase pathway and growth arrest)
Synonyms: STX17-AS1; STX17-DT; LOC101928438
Gene: Long non-coding RNA gene on chromosome 9 (99,355,337 to 99,906,624, reverse strand). Ensembl gene ENSG00000271086.
Diseases named in the same sentence as NAMA in open-access papers:
NAMA is named in the same sentence as 3 diseases in open-access papers, as found by Europe PMC text mining. Sharing a sentence is not in itself a finding about the gene and the disease. The quoted sentences say what the papers report.
thyroid cancer (2 papers, 2014 to 2024). "Another classic oncogenic lncRNA is non-coding RNA associated with the mitogen-activated protein (MAP) kinase pathway and growth arrest (NAMA), which is weakly expressed in thyroid cancer tissues." (PMID 25289082, 2014). "Sedaghati summarized the dysregulated and functional LncRNAs in thyroid cancer, including 28 upregulated LncRNAs, such as ANRIL, BANCR, H19, HOTAIR, MALAT1, and NEAT1, and 22 downregulated LncRNAs, including GAS5, NAMA, PTCSC2, and PTCSC3." (PMID 37874339, 2024).
tumor (2 papers, 2018 to 2023). "Knockdown or depletion of HOTAIR, LOC100507661, NEAT1 as well as overexpression of NAMA can inhibit tumor progression." (PMID 29416703, 2018). "Previous research has found that the expression levels of FAL1, HOTAIR, LOC100507661, NEAT1, NONHSAT076754 are increased, while GASS-AS1, NAMA, NONHSAT037832 are decreased in tumor tissues, which could be indicators for diagnosis." (PMID 29416703, 2018).
NAMA also shares sentences with these, for which no sentence is quoted: thyroid (1 paper).